MIF (macrophage migration inhibitory factor)
Diseases named in the same sentence as MIF in open-access papers (continued):
Sharing a sentence is not in itself a finding about the gene and the disease.
Obesity (continued). "The pleiotropic adipokine and cytokine MIF has been identified in different entities of adipose tissue inflammation including obesity and wound healing, which share a state of tissue hypoxia." (PMID 34366876, 2021). "While D-DT is negatively correlated with obesity and reverses glucose intolerance, MIF is positively correlated with obesity and insulin resistance." (PMID 33776775, 2021). "In the advanced stage of obesity, M1 macrophage-derived MIF further exacerbates both adipocyte inflammation and macrophage polarization in a positive feedback loop, resulting in the exaggeration of adipose tissue inflammation and insulin resistance." (PMID 32265835, 2020). "Then, at an early stage of adipose tissue inflammation, during the development of obesity, adipocyte MIF secretion directly facilitates M1 macrophage polarization via CD74, which is reported to be part of the MIF receptor complex." (PMID 31247902, 2019). "MIF and D‐DT have been reported to be involved in obesity, but there is little known about the regulation of D‐DT in adipose tissue inflammation and wound healing." (PMID 27605340, 2017). "Several groups have investigated adipose tissue as a potential source of circulating MIF in obesity." (PMID 26124760, 2015). "The development of insulin resistance and T2D in obesity is related to elevated MIF levels, which rise with increasing severity of disease." (PMID 26124760, 2015). "This review provides a comprehensive summary of our current knowledge on the role of MIF in obesity, its production by adipose tissue, and its involvement in the development of insulin resistance, type 2 diabetes, and NAFLD." (PMID 26124760, 2015). "In previous reports, both functional MIF polymorphisms have been related with autoimmune/inflammatory pathologies such as RA, SLE, and psoriatic arthritis, as well as obesity and diabetes." (PMID 25972622, 2015). "Subcutaneous abdominal adipose tissue MIF mRNA expression is increased in obesity and is positively correlated with waist circumference." (PMID 26124760, 2015). "Our results suggest the involvement of MIF in the pathophysiology of obesity and its relationship with metabolic comorbidities." (PMID 25972622, 2015). "If indeed the increased levels of circulating MIF in obesity are primarily the result of increased adipose tissue mass and ­adipocyte expansion, one would logically expect plasma MIF levels to decrease when obese subjects lose weight." (PMID 26124760, 2015). "Here, we provide a comprehensive review of the current knowledge on the role of MIF in obesity, MIF production by adipose tissue, and its role in the development of insulin resistance, type 2 diabetes, and NAFLD." (PMID 26124760, 2015). "To confirm the positive relationship between obesity and heightened levels of adipose tissue MIF, we profiled the expression of MIF and its corresponding receptors." (PMID 25412423, 2014). "Circulating MIF levels are elevated during obesity however its role in high-fat diet induced adipose inflammation and insulin resistance remains elusive." (PMID 25412423, 2014). "It has been shown previously that systemic concentrations of MIF are elevated in patients with obesity, impaired glucose tolerance and type 2 diabetes." (PMID 21283592, 2011). "In the past few years, studies in experimental models of disease have provided some confirmatory data indicating a mechanistic role for MIF in the comorbidities of obesity." (PMID 20169173, 2010). "Elevated levels of MIF or its cell surface receptor (CD74) were found in patients with diabetic complications including diabetic nephropathy, diabetic retinopathy, and diabetic foot syndrome further supporting a role of MIF in the comorbidities of obesity." (PMID 20169173, 2010). "This hypothesis is supported by the observation that MIF mRNA expression was decreased in the epididymal fat of rats with obesity and diabetes." (PMID 39963593, 2025).
Obesity (continued). "Furthermore, MIF is a pro‐inflammatory cytokine involved in the regulation of insulin resistance and obesity." (PMID 39963593, 2025). "Furthermore, blocking the extracellular action of MIF by a neutralizing MIF antibody significantly reduced obesity and insulin resistance in HFD mice, suggesting a critical role for extracellular MIF in regulating metabolism through downregulation of HSL." (PMID 37935315, 2024). "Previous studies also have shown that obesity induces adipose MIF expression and cellular release." (PMID 37935315, 2024). "Further investigations on primary monocyte subsets in larger cohorts in correlation with adipose tissue-infiltrating macrophages are needed to unravel the impact of monocytic CXCL10/CX3CR1/MIF signaling on obesity-related systemic inflammation and its concomitant diseases." (PMID 38175171, 2024). "Our data suggest that HSL regulation by MIF is an important molecular mechanism that could exacerbate obesity in HFD." (PMID 37935315, 2024). "Indeed, OLZ monotherapy in SZ patients for two months also elevated plasma MIF levels, thereby contributing to insulin resistance, obesity, and hyperlipidemia." (PMID 38802393, 2024). "Targeting low levels of MIF could be tried by treatment with the anti-obesity drug pioglitazone as it may reduce CVD and increase MIF expression." (PMID 37430349, 2023). "MIF may also regulate obesity through its transcriptional activity on genes directly associated metabolism and energy homeostasis, which may be a future research direction." (PMID 38052787, 2023). "In the present study, obesity significantly suppressed the MIF/AMPK pathway response to exhaustive exercise-induced fatal stress, as indicated by the lower levels of MIF mRNA and protein, pAMPK, and the ratio of pAMPK/AMPK in the myocardium of mice after exhaustive exercise." (PMID 37711889, 2023). "In line with previous reports that suggest an inhibitory role of MIF in wound repair, this could play an important part in the pathologic healing pathway in the obesity-induced phenotype." (PMID 38139127, 2023). "Since MIF is involved in the development of insulin resistance, associated with diabetes and obesity, and MV-associated MIF triggered rapid ERK1/2 activation in macrophages, the authors suggested that MIF pathway should be reconsidered in the context EV-associated form." (PMID 34123416, 2021). "In general, MIF may be a potential therapeutic target for obesity related tumors and it also has a significant contribution to improve the early detection rate of ovarian cancer." (PMID 34485124, 2021). "Adipocytes are important endocrine cells in the tumor microenvironment of obesity-related tumors, which can secrete a variety of adipokines (such as leptin, adiponectin, estrogen, resistin, MIF and MCP-1, etc.), among which leptin, adiponectin and estrogen are the most in-depth and valuable ones." (PMID 34485124, 2021). "The possible pathophysiological rationales may be that MIF could increase CAD susceptibility by affecting the metabolism of glycolipid, obesity and inflammation." (PMID 35046995, 2021). "Furthermore, the progression of obesity-related tumors is determined by the interaction of many factors, and resistin, MIF and MCP-1 play an important role in this process." (PMID 34485124, 2021). "In obesity, the cytokine MIF is enhanced and linked to obesity-associated inflammation and IR, indicating that it may be a primary cytokine promoting ATM recruitment during obesity." (PMID 28661198, 2018). "However, others studies have shown increased MIF serum levels in subjects with obesity and type 2 diabetes." (PMID 25972622, 2015). "Besides adipose tissue as a possible source of circulating MIF in obesity, there are some reports on MIF expression by mononuclear cells (MNCs), with reports of increased MIF mRNA expression by MNC from obese subjects." (PMID 26124760, 2015). "MIF in experimental models of obesity and insulin resistance/T2D." (PMID 26124760, 2015).
Obesity (continued). "In addition, future studies assessing the complex interplay between metabolic and inflammatory balances will greatly enhance our understanding of the development of obesity-related diseases, and the role of MIF therein." (PMID 26124760, 2015). "The relationship between obesity and MIF is not consistent and any causal relationship between obesity and MIF levels remains to be established." (PMID 25972622, 2015). "This suggests that MIF-inducing processes unrelated to obesity/adiposity and adipose tissue expression may contribute to circulating MIF levels as overweight/obesity progresses to T2D." (PMID 26124760, 2015). "Furthermore, we summarize findings from experimental disease models studying the contribution of MIF in obesity and insulin resistance, type 2 diabetes, and hepatic lipid accumulation and fibrosis." (PMID 26124760, 2015). "Moreover, serum MIF levels are elevated in patients with obesity and type 2 diabetes and mRNA levels of MIF in subcutaneous abdominal adipose cells are positively associated with adipocyte size and insulin resistance." (PMID 22428043, 2012). "MIF deficiency did not affect adipose mass or obesity, but the adipocytes of MIF deficient mice however were found to be smaller in size, beginning at a young age (12–18 weeks)." (PMID 20169173, 2010). "Several lines of clinical evidence support a relationship between MIF and obesity." (PMID 20169173, 2010). "Because host MIF is known to promote adipogenesis and amplify inflammatory signaling, this finding provides important evidence that T. spiralis MIF may counter-regulate host MIF signaling, contributing to its anti-inflammatory and anti-obesity effects." (PMID 41596532, 2026). "In addition, long-term and tissue-specific investigations may help clarify how rTs-MIF contributes to the maintenance of immune–metabolic homeostasis in obesity." (PMID 41596532, 2026). "As rTs-MIF does not directly target the pathways associated with adverse gastrointestinal, neurological, or cardiovascular effects commonly observed with current anti-obesity drugs, it is expected to have a lower risk of long-term side effects." (PMID 41596532, 2026). "The loss of Pref-1 increases adipose MIF secretion contributing to non-inflammatory IR in obesity." (PMID 37283810, 2023). "However, which enzymatic activity of MIF is responsible for regulating in obesity are still unknown." (PMID 32265835, 2020). "Our study population was nonobese and consisted mostly of men, indicating that MIF may be associated with the predisposition to T2D even in the absence of obesity." (PMID 30302090, 2018). "Of note, circulating MIF may also be produced by other tissues and cells in obesity." (PMID 26124760, 2015). "The involvement of sources of inflammation other than adipose tissue may explain that the associations of MIF and metabolic disease (metabolic syndrome, insulin resistance, T2D) appear to be independent of obesity with increasing complexity of disease." (PMID 26124760, 2015). "Additionally, MIF involvement has been demonstrated in immunological and inflammatory diseases such as septic shock, cancer, and chronic diseases including bowel disease, rheumatoid arthritis, colitis, obesity, and diabetes." (PMID 24527464, 2014). "WT mice fed high fat diet (HFD), as well as mice overexpressing MIF, both had high circulating MIF levels and showed suppression of HSL during the development of obesity." (PMID 37935315, 2024). "In contrast, our present findings suggest that extracellular MIF contributes to both HSL downregulation and adipocyte hypertrophy and obesity." (PMID 37935315, 2024). "Both intracellular and extracellular MIF have opposing effects to regulate HSL, but extracellular actions predominate to downregulate HSL and exacerbate the development of obesity during HFD." (PMID 37935315, 2024). "The candidate genes MIF, MAP2K3, HACD3, and MEGF11 excavated in this study are related to obesity and fat deposition." (PMID 39330807, 2024).
Obesity (continued). "We have shown significant correlations between plasma MIF and CX3CR1 expression on all three monocyte subsets in patients with obesity." (PMID 38175171, 2024). "To further examine whether the MIF/AMPK/HSL signaling pathway contributes to the development of adipocyte hypertrophy and obesity in vivo, we utilized a MIF overexpression model, with transgenic over-expression of MIF (Mif lung Tg mice) leading to chronic elevation of circulating MIF." (PMID 37935315, 2024). "Extracellular MIF has an important role in the downregulation of HSL and lipolysis and contributes to adipocyte hypertrophy and obesity during HFD." (PMID 37935315, 2024). "In contrast, MIF and DDT play a different role in physiological processes such as adipogenesis and correlate differently with obesity." (PMID 38275363, 2023). "In summary, these data support a novel, inflammation-independent PAR2/Pref-1/MIF pathway that acts between Pref-1+ cells and mature adipocytes to regulate WAT MIF release in obesity related IR." (PMID 37283810, 2023). "In obesity, adipocyte COX-2 activation seems to upregulate the macrophage migration inhibitory factor (MIF) production via NF-κB activation." (PMID 37252693, 2023). "In obese animals, batosomes are enriched with proteins involved in signal transduction, cell communication, the immune response, inflammation, thermogenesis, and as obesity biomarkers including UCP1, Glut1, MIF, annexin A6, CD14, and ceruloplasmin." (PMID 36142750, 2022). "Other cytokines and myokines, such as macrophage migration inhibitory factor (MIF), are elevated in inflammatory conditions such as obesity and T2D and have modulatory roles in glucose homeostasis." (PMID 33101053, 2020). "As in T1DM, MIF is highly expressed in T2DM complications such as myocardial damage, coronary artery disease, diabetic retinopathy, obesity, and metabolic syndrome." (PMID 24527464, 2014). "Due to the large number of studies that support this idea, we can conclude that MIF is a proinflammatory cytokine with great importance not only during the course of diabetes but also before the establishment of diabetes and in the risk factors of disease such as obesity." (PMID 24527464, 2014). "The macrophage migration inhibitory factor (MIF) is a 115-amino acid secreted cytokine that is involved in a number of pathological conditions, including autoimmunity, obesity and cancer." (PMID 23497377, 2013). "Differences in the exposed loop regions of helminth MIF may differentially affect its interactions with CD74 or other receptors, thereby conferring anti-inflammatory and anti-obesity properties." (PMID 41596532, 2026). "By screening adipogenesis genes, we also found that MIF deletion increased LPL gene expression in adipose tissue which may also contribute to the development of adipocyte hypertrophy and obesity." (PMID 37935315, 2024). "•Extracellular MIF predominates to downregulate HSL and exacerbate obesity during HFD." (PMID 37935315, 2024). "Thus, our present data suggest that both intracellular and extracellular MIF have opposing effects to regulate HSL, but the extracellular actions predominate to downregulate HSL and exacerbate the development of obesity during HFD." (PMID 37935315, 2024). "An anti-MIF antibody and the absence of MIF inhibited glucose-stimulated insulin release resulting in the development of obesity, glucose intolerance and hyperglycemia." (PMID 35091838, 2022). "We have also observed similar findings in this study, whereby TNF-α, IL-6, IL-8, MIF and PIA-1 were significantly associated with OSA was independent of the degree of obesity." (PMID 34086720, 2021). "At the same time, it briefly describes the cancer-promoting mechanism of resistin, MIF and MCP-1 in obesity-related tumors, and finally summarizes the specific treatment opinions and measures for various adipokines and insulin/insulin-like growth factors in recent years." (PMID 34485124, 2021).
Obesity (continued). "Although it has been reported that MIF deficiency alleviated HFD-induced obesity, the role of the tautomerase of MIF in HFD-induced obesity was not explored." (PMID 32265835, 2020). "In this study, we focused our attention on effects of tautomerase activity-lacking of MIF on obesity induced by HFD." (PMID 32265835, 2020). "In the present study, we investigated the roles of the tautomerase of MIF in high fat diet (HFD)-induced obesity using MIF tautomerase activity-lacking (MIFP1G/P1G) mice." (PMID 32265835, 2020). "Taken together, our results indicated that tautomerase activity-lacking of MIF alleviated HFD-induced obesity." (PMID 32265835, 2020). "Macrophage migration inhibitory factor (MIF) has multiple intrinsic enzymatic activities of the dopachrome/phenylpyruvate tautomerase and thiol protein oxidoreductase, and plays an important role in the development of obesity as a pro-inflammatory cytokine." (PMID 32265835, 2020). "Taken together, our results demonstrated that the tautomerase activity-lacking of MIF significantly alleviated the HFD-induced obesity and adipose tissue inflammation, and improved insulin resistance in MIFP1G/P1G mice." (PMID 32265835, 2020). "This survey aims to advance our understanding on the functions of MIF in non-pathological and pathological processes connected to obesity and glucose homeostasis, with particular emphasis on adipose tissue and liver." (PMID 26124760, 2015). "Within PCOS patients, the effect of obesity is not ­significant due to large variation within this population, and comparable plasma MIF levels were found in non-obese and obese patients [~35 and ~55 ng/ml, respectively, in Ref." (PMID 26124760, 2015). "As with neutralizing MIF, CD74 knockout also significantly reduced adipocyte hypertrophy and body weight gain following HFD feeding, suggesting that CD74 may be a key regulator of the MIF/AMPK/JNK/HSL pathway during obesity." (PMID 37935315, 2024). "However, it is currently unknown whether MIF directly downregulates HSL and thus the development of adipocyte hypertrophy during obesity." (PMID 37935315, 2024). "However, the current results show that the cytokine, MIF, expressed upstream of these cytokines, inhibits HSL and lipolysis in adipose tissue, thereby exacerbating adipocyte hypertrophy and contributing to the development of obesity." (PMID 37935315, 2024). "However, in the context of non-inflammatory obesity, the ability of Pref-1 to inhibit MIF release from Pref-1+ cells and adipocytes is impaired; consequently, circulating plasma MIF levels are increased." (PMID 37283810, 2023). "Whether PAR2 has additional distinct actions on lipid metabolism independent of its effects on Pref-1 and MIF against obesity will also be of interest for further studies." (PMID 37283810, 2023). "To investigate whether Pref-1 mediates non-inflammatory MIF release, we employed a non-inflammatory mouse model of obesity." (PMID 37283810, 2023). "Thus, in obesity, batosomes are enriched with proteins involved in signal transduction, cell communication, the immune response, inflammation, thermogenesis, and potential obesity biomarkers including UCP1, Glut1, MIF, and ceruloplasmin." (PMID 36142750, 2022). "In the present study, in order to determine the roles of MIF enzymatic activity in HFD-induced obesity, the knock-in transgenic mice with the tautomerase activity-lacking of MIF (MIFP1G/P1G) were generated by replacing the proline of N-terminal of the exon 1 with glycine." (PMID 32265835, 2020). "The tautomerase -lacking of MIF protected mice from HFD-induced obesity in MIFP1G/P1G mice." (PMID 32265835, 2020). "In later stages of obesity-associated T2D, MIF levels appear to be elevated independent of obesity and adiposity, indicating that with increasing disease complexity, other sources of inflammation may contribute to circulating MIF levels." (PMID 26124760, 2015).